KRT19 (keratin 19)
Diseases named in the same sentence as KRT19 in open-access papers (continued):
Sharing a sentence is not in itself a finding about the gene and the disease.
lung carcinoma (continued). "The researchers also compared miR-1290 with the traditional lung cancer tumor markers-carcinoembryonic antigen (CEA), cytokeratin-19 fragment (CYFRA21-1), and neuron-specific enolase (NSE) using the ROC curve." (PMID 40636359, 2025). "Several emerging serologic biomarkers have been applied in clinical use for early lung cancer screening and diagnosis such as carcinoembryonic antigen (CEA) and serum cytokeratin 19 fragments (CYFRA 21‐1), which can be analysed conveniently and economically." (PMID 40714929, 2025). "X-ray examination is important to avoid bias in the presence of other diseases that can increase the production of cytokeratin-19 fragments (CYFRA 21-1), i.e., lung cancer." (PMID 40469991, 2024). "Some lung cancer-related markers, including CEA, carbohydrate antigen 125 (CA125), cytokeratin 19 fragment (CY211), NSE, and SCC, have been widely reported." (PMID 38315228, 2024). "Several tumor markers for lung cancer have been identified and applied in the clinical diagnosis of lung cancer, such as neuron-specific enolase (NSE), glycoprotein antigen 153 (CA153), cytokeratin 19 fragment (CYFRA21-1) and glycoprotein antigen 125 (CA125)." (PMID 34630106, 2021). "However, the value of KRT19 in lung cancer is still unknown." (PMID 33442422, 2021). "KRT19, SPARC, SPOCK, LINC00707 (lung cancer promoting lincRNA), FOSL1 and AXL (identified as downstream targets of TS as they appeared in both signatures) were qPCR validated in both cell lines." (PMID 33024270, 2021). "The C-terminus of cytokeratin 19 (CYFRA 21-1) is a lung-specific marker with the sensitivity and specificity of 43% and 89%, respectively, that are very low for lung cancer screening." (PMID 33143045, 2020). "Lung cancer serum tumor markers including carcinoembryonic antigen (CEA), cytokeratin 19 fragment (CYFRA21‐1), and carbohydrate antigen 125(CA125) as prognostic predictors is controversial." (PMID 32725794, 2020). "Some lung cancer-related markers, including carcinoembryonic antigen (CEA), carbohydrate antigen 125 (CA125), cytokeratin 19 fragment (CY211), neuron-specific enolase (NSE), and squamous cell carcinoma antigen (SCC), have been widely reported." (PMID 30364165, 2018). "Also, combined miRNAs with serum protein markers, such as cytokeratin 19 fragment (CYFRA21-1), carcinoembryonic antigen (CEA), neuron-specific enolase (NSE), cancer-associated antigen (CA) 125 and CA 19-9 maybe more effective in the diagnosis of lung cancer." (PMID 29163821, 2017). "For lung cancer diagnosis, the leading markers used are carcinoembryonic antigen (CEA), cytokeratin 19 fragments (CYFRA 21–1) and neuron-specific enolase (NSE)." (PMID 28152979, 2017). "The roles of carcinoembryonic antigen (CEA), cytokeratin 19 fragments (CYFRA21-1) and neuron-specific enolase (NSE) in metastases occurrence and poor diagnosis in specific histological classifications of lung cancer need further exploring." (PMID 28152979, 2017). "Further studies should be performed to understand how the cooperative expression of KRT19 and HER2 contributes to malignant potential of lung cancer." (PMID 28008968, 2016). "The most widely used lung cancer biomarkers are carcinoembryonic antigen (CEA), cancer antigen 125, cytokeratin 19 fragment (CYFRA21-1), and neuron-specific enolase." (PMID 25961003, 2015). "Furthermore, the specificity and sensitivity of standard tumor markers, including carcinoembryonic antigen (CEA) and cytokeratin 19 fragment (CYFRA21-1), require further refinement for effective diagnosis and prognostic evaluation of lung cancer." (PMID 41394878, 2025). "Cytokeratin 19 fragment (CYFRA 21-1), a common lung cancer–related biomarker, is elevated in bronchoalveolar lavage fluid of patients with acute respiratory distress syndrome (ARDS), as well as in the serum of patients with interstitial lung diseases and radiation pneumonitis." (PMID 41487633, 2025).
lung carcinoma (continued). "Lung cancer was not excluded based on patient age, respiratory symptoms, elevated cytokeratin 19 fragments, carcinoembryonic antigen, and imaging findings." (PMID 40489825, 2025). "A previous investigation reported on the concentrations of three tumor markers, CEA, cytokeratin 19 fragments (CYFRA 21-1), and neuron-specific enolase (NSE), in CSF of 35 lung cancer patients with meningeal carcinomatosis of lung cancer and 35 patients with benign brain tumors." (PMID 38001599, 2023). "In the present study, we focused on KRT13 as a candidate radioresistance gene because certain keratins (KRTs) are reportedly shown to have cancer stem-like properties, including KRT19 in hepatocellular carcinoma and colorectal cancer, KRT6 in lung cancer and KRT17 in cervical cancer." (PMID 36610719, 2023). "In addition, the assessment of blood circulating proteins like CEA, CYFRA 21-1 (serum cytokeratin 19 fragment), fibrinogen, C-reactive protein (CRP), and neuron-specific enolase (NSE), as markers of lung cancer progression, has been considered inconclusive." (PMID 36213817, 2022). "Do we need validation studies for the KRT19 mRNA copy numbers set up as cut-off for negative micro- and −macrometastasis in lung cancer?" (PMID 31331335, 2019). "Moreover, KRT19 transcription was reported to be augmented by activation of the HER2/ERK/SP1 signaling pathway, resulting in translocation of KRT19 to the HER2 receptor; consequently, HER2 activation was stabilized in breast and lung cancers." (PMID 30650643, 2019). "Further studies may lead to establish a new therapeutic strategy targeting KRT19 and HER2 in HER2-activated malignant tumors including lung cancer." (PMID 28008968, 2016). "In lung cancer, CEA is a sensitive marker for adenocarcinoma, while squamous cell carcinoma antigen and cytokeratin 19 fragment are markers for squamous cell carcinoma, and neuron-specific enolase and progastrin-releasing peptide are markers for small cell carcinoma 17,18." (PMID 26310928, 2015). "An assay measuring soluble cytokeratin 19 fragments in the circulation, CYFRA 21-1, is a particularly useful tool in lung cancer and is mainly used in monitoring treatment and evaluating response to therapy in lung cancer." (PMID 25006982, 2014). "Notably, two lung cancer-specific biomarkers, neuron-specific enolase (NSE) and cytokeratin 19 fragment (CYFRA21-1), persisted at abnormally elevated levels, potentially reflecting the gastric tumor’s dual epithelial origin and neuroendocrine differentiation features of the gastric tumor." (PMID 40977702, 2025). "This study aimed to assess a four-marker protein panel (4MP)’s performance, including the precursor form of surfactant protein B, cancer antigen 125, carcinoembryonic antigen, and cytokeratin-19, for predicting lung cancer in a cohort enriched with never- and ever-smokers." (PMID 38893188, 2024). "Moreover, serum biomarker examination for lung cancer were abnormal as follows: carcinoembryonic antigen (CEA) at 13.74 ng/mL, cytokeratin 19 fragment (CYFRA21-1) at 6.82 ng/mL, neuron-specific enolase (NSE) at 25.49 ng/mL, and progastrin-releasing peptide precursor (ProGRP) at 89.35 pg/mL." (PMID 39850892, 2024). "Additionally, serum biomarkers of lung cancer were abnormal as follows: carcinoembryonic antigen (CEA) at 13.74 ng/mL, cytokeratin 19 fragment (CYFRA21-1) at 6.82 ng/mL, neuron-specific enolase (NSE) at 25.49 ng/mL, and progastrin-releasing peptide precursor (ProGRP) at 89.35 pg/mL." (PMID 39850892, 2024). "However, KRT19 has not been well characterized in lung cancer, specifically with regard to the prognostic value." (PMID 33442422, 2021). "Furthermore, it is demonstrated that KRT19 transcription could be increased through HER2/ERK/SP1 signaling pathway, in a consequence, KRT19 translocated to HER2 receptor then bound and stabilized the HER2 activation in breast and lung cancer." (PMID 29747452, 2018).
lung carcinoma (continued). "Furthermore, in lung carcinomas with low or no expression of KRT19, such as small cell carcinomas, the inclusion of a second or third marker could minimise false negatives and improve the specificity of the test." (PMID 31331335, 2019). "Lung cancer markers, including carcinoembryonic antigen (CEA), neuron-specific enolase (NSE), squamous cell carcinoma (SCC) antigen, and cytokeratin 19 (CK19), have been generally utilized to identify malignant and nonmalignant pleural effusions." (PMID 23759037, 2013). "Besides, we calculated the 5hmC level of clinically known but nonspecific markers for lung cancer in control and tumor groups, including CEA, CA125 (MUC16), NSE (ENO2), and CYFRA21-1 (KRT19)." (PMID 30010036, 2018).
hepatocellular carcinoma (109 papers, 2009 to 2026). A malignant tumor that arises from hepatocytes. "The study investigated Cytokeratin 19 (CK19), a stem cell marker associated with the progenitor subtype, which has been linked to heightened recurrence and therapy resistance in hepatocellular carcinoma." (PMID 38139085, 2023). "For instance, KRT19 was shown to be a cancer stem cell marker in hepatocellular carcinomas, associated with poor overall survival." (PMID 35078507, 2022). "In hepatocellular carcinoma, keratin 19 was associated with larger tumor size as well as more invasive features, indicating worse prognosis." (PMID 32181476, 2020). "Keratin 19 (K19) is a cancer stem cell marker expressed by a subpopulation of hepatocellular carcinoma (HCC), associated with tumor aggressiveness." (PMID 32998218, 2020). "After 2–3 weeks, these mice developed multifocal liver carcinomas with glandular structures, high KRT19 levels and low HNF4α expression." (PMID 39948437, 2025). "KRT19 expression was found to be the independent prognostic factor for hepatocellular carcinoma and pancreatic ductal adenocarcinoma with LN metastasis." (PMID 37142981, 2023). "A report suggested that a high level of KRT19 showed the strongest correlation with increased tumor size and metastasis, and knockdown of KRT19 inhibited invasion of hepatocellular carcinoma." (PMID 37371833, 2023). "LAMB1 is upregulated in hepatocellular carcinoma tissues and its co-expression with keratin-19 leads to poor prognosis and shortened survival in these patients." (PMID 36984512, 2023). "Regarding CSCs, high KRT19 expression is correlated with cancer stemness and radioresistance in hepatocellular carcinoma and colorectal cancer." (PMID 36610719, 2023). "According to studies, KRT19 expression engages adverse tumor differentiation and aggressive behavior in hepatocellular carcinoma." (PMID 36522691, 2022). "Alternatively, silencing of KRT19 inhibited hepatocellular cancer (HCC) and cancer stem cell progression by correlating with oncogenic microRNAs, invasive/metastasis markers, and the TGFβ/Smad signaling pathway." (PMID 30650643, 2019). "For instance, in liver tumors (hepatocellular carcinoma and cholangiocarcinoma) YAP1 cytoplasmic expression was associated with keratin 19 expression which was associated with cancer aggressiveness and patients' poor prognosis." (PMID 29850494, 2018). "The combination of GPC3 and cytokeratin 19 expression in the cancer tissue was suggested as an independent prognostic indicator in patients with hepatocellular carcinoma." (PMID 28510121, 2017). "Upregulated expression of cytokeratin-19 (CK-19), the parent protein of CYFRA 21-1, has proven to be an independent risk factor of intraliver and lymph node metastasis in hepatocellular carcinoma." (PMID 28298807, 2017). "As widely known, keratin 19 (K19) is a marker of strong invasion and poor prognosis in the hepatocellular carcinoma (HCC) of human beings." (PMID 28819584, 2017). "Staining for the hepatocellular carcinoma marker cytokeratin-19 (CK19) further confirmed the observations with the H&E staining and revealed typical and expected cytological characteristics of the transplanted HCCLM3 cells." (PMID 25625591, 2015). "Based on this theory, we aimed to explore the regulatory mechanisms of Linc00974 and KRT19 (an lncRNA beyond the Flank10kb class with protein) when we first confirmed the aberrant expression in hepatocellular carcinoma in a previous study." (PMID 25476897, 2014). "In hepatocellular carcinoma, KRT19 enhances the interaction of histone deacetylase 1 and REST corepressor 1 to increase the deacetylase activity of the corepressor of RE-1 silencing transcription factor (CoREST) complex, resulting in dedifferentiation and tumorigenesis." (PMID 41345704, 2025). "In addition, downstream transcription activators AP1 and SP1 of ERK1/2 activate the expression of KRT19 in hepatoma cells." (PMID 34659572, 2021).
hepatocellular carcinoma (continued). "KRT19 acts as a key molecule in hepatocellular carcinoma invasion and angiogenesis." (PMID 32519739, 2020). "The hepatocellular carcinoma cells positive to both GPC3 and cytokeratin 19 were found to have the highest risk of multifocality, microvascular invasion, regional lymph node involvement, shortest recurrence time, and distant metastasis in a retrospective study of immunohistochemical staining." (PMID 28510121, 2017). "The expression of Keratin 19 (K19) was reported in a subset of hepatocellular carcinomas (HCCs)." (PMID 20167095, 2010). "MYH9 can also interact with GSK3β and facilitate GSK3β ubiquitination and degradation to favor cancer stemness properties in hepatocellular carcinoma, illustrating that KRT19/MYH9 may coordinate cell fate specification via orchestrating regulatory hubs with GSK3β." (PMID 41345704, 2025). "Cytokeratin 19-positive (CK19+) hepatocellular carcinoma (HCC) is an aggressive subtype characterized by early recurrence and chemotherapy tolerance." (PMID 34785656, 2021). "Recent studies have revealed that KRT19 is crucially involved in the cancer stemness of hepatocellular carcinoma (HCC)." (PMID 29747452, 2018). "Cytokeratin 19 (CK-19) is a prognostic indicator of recurrence and metastasis of hepatocellular carcinoma (HCC) following radical resection." (PMID 26588210, 2015). "Cytokeratin 19 (CK19), Ki67 antigen (Ki67), and β-catenin are abnormally overexpressed in hepatocellular carcinoma (HCC), but their diagnostic and prognostic value remains unclear." (PMID 41388520, 2025). "One subtype of hepatocellular carcinoma (HCC), with cytokeratin 19 expression (CK19+), has shown to be more aggressive and has a poor prognosis." (PMID 36814805, 2023). "Cytokeratin 19 (CK19) in liver is a marker to differentiate between CCA and hepatocellular carcinoma, which stains negatively in hepatocytes and positively staining due to CCA originating from epithelial." (PMID 37932819, 2023). "The “five-gene” score (TAF9, RAMP3, HN1, KRT19, and RAN) was built to evaluate the genetic role in hepatic carcinoma and reported strong prognostic relevance." (PMID 35200757, 2022). "Protein expression of cytokeratin 19 (CK19) in HCC was low, however, it would reflect the malignant progression of hepatoma cells." (PMID 35186756, 2022). "There is currently only one report that suggests KRT19 as a CSC marker in hepatocellular carcinoma (HCC), while another recent study demonstrated that inter-keratin fusions between KRT6 and KRT14 could promote cancer stemness in OSCC." (PMID 35706019, 2022). "In hepatocellular carcinoma, hepatocyte growth factor activates the c-MET and MEK-ERK1/2 pathways, and upregulates the expression of KRT19." (PMID 34659572, 2021). "Interaction of hsa-mir-642a-5p and Linc00974 can increase the expression of keratin 19 and activate Notch and TGF-β signaling pathways, which will increase the proliferation and invasion of hepatocellular carcinoma." (PMID 29513728, 2018). "Cytokeratin-19 (CK19) and glypican-3 (GPC3) are both routine pathological diagnosis biomarkers for the primary carcinoma of the liver." (PMID 28276470, 2017). "The metastasis of HCC involves in elevating expression of metastasis‐related molecules, including keratin 19 (K19) 9, epithelial cell adhesion molecules (EpCAM) 10, matrix metalloproteinase 2/9 (MMP2/9) 11 and CXCR4 12 in hepatoma cells." (PMID 26756858, 2016). "KRT19 was identified as one of the key biomarkers for distinguishing cholangiocarcinoma (CCA) and hepatocellular carcinoma." (PMID 27833076, 2016). "Cytokeratin 19 (CK19) is well acknowledged as a marker of biliary/progenitor cells and tumor stem cells and represent a vital marker of the proliferative subtype in Hepatocellular Carcinoma (HCC)." (PMID 41293267, 2025).
hepatocellular carcinoma (continued). "Key markers, such as PTPRC, CD3E, CD4, CD79A, and CD3G in immune cells, EPCAM and KRT19 in epithelial cells, and MME and PECAM1 in stromal cells, were identified, providing crucial insights into hepatocellular carcinoma progression and immune response mechanisms." (PMID 39388011, 2024). "Thus, we analyzed the expression of epithelial surface protein (EpCAM) and cytoskeleton protein cytokeratin 19 (CK19), both of which are enriched in liver carcinomas with stem cell features, in the rosette cells." (PMID 35879421, 2022). "In patients with hepatocellular carcinoma (HCC) recurrence, the majority of hepatic stem/progenitor cell (HSC/HPC) biomarkers are overexpressed, including cytokeratin 19, ABCG2, CD133, Nestin, and CD44, and angiogenesis agents CD34, VEGF, and PD-ECGF." (PMID 32466488, 2020). "OATP1B3, a transporter of bile acids, was found to be highly expressed in green hepatoma, and HCCs with high expression of OATP1B3 were negative for cancer stem cell markers, including cytokeratin-19 (CK19) and EpCAM." (PMID 35053606, 2022). "In immunohistochemical (IHC) tests, the adenocarcinoma cells were positive for cytokeratin-7 (CK7), cytokeratin-19 (CK19), CD56, and epithelial membrane antigen (EMA), but negative for hepatocellular carcinoma markers such as Glypican-3 (date not shown)." (PMID 30478801, 2018). "Therefore, we examined the expression pattern of YAP and TAZ in 141 patients with hepatocellular carcinoma keratin 19 positive (HCC K19+), hepatocellular carcinoma keratin 19 negative (HCC K19−), combined hepatocellular–cholangiocarcinoma carcinoma (cHCC-CCA), or cholangiocarcinoma (CCA)." (PMID 30717258, 2019).